CD34 (CD34 molecule)
Diseases named in the same sentence as CD34 in open-access papers (continued):
Sharing a sentence is not in itself a finding about the gene and the disease.
tumor (continued). "Morphologically, the tumor displays an undifferentiated and/or rhabdoid phenotype and exhibits the expression of one or more stem cell markers, including CD34, SOX2, and SALL4." (PMID 38265099, 2024). "Closer examination of the expression markers associated with cluster 44 revealed expression of both CD45 (indicating a hematopoietic cell) and tumor endothelial marker CD34." (PMID 39761010, 2024). "In the comparison of PVPR with baseline clinical features, we also found that PVPR was significantly related to tumor size, gastrointestinal bleeding, mitotic index, NIH risk category, CD34, and Ki-67." (PMID 39582542, 2024). "Analysis of spatial interactions of VEGF+/– macrophages to CD34+ endothelial cells in HCC tumor tissue from these 8 patients identified that VEGFA+ and VEGFA– macrophages preferentially reside 0–20 μm from CD34+ endothelial cells." (PMID 39761010, 2024). "We reconstituted human immunity in these mice with human cord blood hematopoietic stem cells (CD34 + ) for human tumor cell experiments." (PMID 38253555, 2024). "Fc-EndoP125A treatment did not decrease the total amount of tumor vasculature, but mice exhibited smaller tumor vessels and markedly decreased CD34+ and LyVE-1+ tumor vessel density compared to PBS- and Rituximab-treated mice." (PMID 39594584, 2024). "Another subset of these cells, CD34+ progenitor cells, represents endothelial progenitor cells, that, in response to certain pro-angiogenic tumor factors, migrate into TIME, differentiate into mature endothelial cells and promote angiogenesis." (PMID 39020414, 2024). "RPTOR knockdown reduced the expression of the proliferation marker Ki67 in tumor tissues and CD34-positive microvessel density (MVD) in the peritumoral area." (PMID 38163890, 2024). "We then performed IHC staining, the results showed that a marked decreased expression of CD34 was observed in tumor sections from PAD4 KO mice." (PMID 38326837, 2024). "The connection between SELP and CD34 shows that patients gain from the stimulation of the innate immune response to improve anti-tumor immunity, eliminate tumor cells, and hinder the growth of tumors." (PMID 37818360, 2023). "For instance, (the rare) neoplastic CD34+ cells were found in tumor 1, tumor 3, tumor 4, and tumor 5 by snRNA-seq and/or CITE-seq." (PMID 36966348, 2023). "The tumor can show variable expression of cytokeratins, CD34, desmin, SMA, claudin 1, and muscle‐specific actin and is consistently negative for S100 protein, Kit, and GFAP." (PMID 36074249, 2023). "These authors also demonstrated experimentally that CD34 can be targeted and downregulated in GISTs by miR-665 and so decrease vascular density in the tumor microenvironment." (PMID 37894282, 2023). "Clinical and pathological factors in 208 patients were compared between two groups [tumor with CD34 (+) vs. CD34 (−)]." (PMID 36910263, 2023). "By comparing CD34 knockout mice with wild-type mice, they were able to demonstrate the importance of CD34 in angiogenesis and tumor growth." (PMID 37241170, 2023). "The release of cytokines IL-1β, IL-6, IL-8, and TNF-α was analyzed in the supernatants of tumor cells (24 h) and CD34+ HSCPs (24, 48, 72 h) after IR (single-dose: 9 Gy) in order to investigate the influence of IEPA on inflammatory responses." (PMID 36903253, 2023). "Tumour cells in the lipogenic area were intensely positive for S100 and p16, and CD34 staining highlighted an arborizing capillary network." (PMID 37241198, 2023). "Following tumor growth, we assessed tumor volume as well as CD34 and Ki67 expression levels to indicate the angiogenic and tumor proliferation abilities, respectively." (PMID 37057280, 2023).
tumor (continued). "In 2006, a group of researchers led by Clarke published a study on the potential involvement of CD34 in tumor development." (PMID 37241170, 2023). "When we assessed the TLS+_Luminal A-BC cases subgroup, we found that BMI was significantly correlated to IMBV_CD34+/SMA− tumor stroma vessel density (p = 0.015)." (PMID 37190085, 2023). "The pathology ofMIAB confirmed GIST and immunohistology showed that the tumor was a Ki-67 4%, CD34+, CD117+,and DOG-1+." (PMID 36632625, 2023). "Immunohistochemistry using anti-CD34 antibody was used to identify micro-vessels, and anti-CD-68 antibody was used to identify TAMs in tumour tissues." (PMID 37052868, 2023). "Divergent expression of CD34 and αSMA in normal breast stromal fibroblasts and tumor stroma CAFs was previously observed and reported by several authors." (PMID 37568639, 2023). "In contrast to VM, presence of CD31 or CD34 in cells that co-expressed tumour markers (e.g. EGFR amplification) or stem cell markers (e.g. CD133, Nestin) indicated vessels containing endothelial cells resulting from transdifferentiation of GSCs." (PMID 36823554, 2023). "CD34 staining of excised tumour tissue was performed and baseline blood samples were analysed for lactate dehydrogenase (LDH) and angiopoietin-2 (ANGPT-2)." (PMID 36718357, 2023). "Immunohistochemical results revealed positive CD31 and CD34 staining of the vessel walls of the HBL tumor, specifically in the endothelial cells, revealing the highly vascular nature of this hemangioblastoma tumor surrounding the neoplastic stromal cells." (PMID 37273678, 2023). "These CD34-positive CSCs have been shown to have enhanced self-renewal ability and increased tumor-initiating capacity compared to CD34-negative cells." (PMID 37241170, 2023). "Superficial CD34-positive fibroblastic tumor (SCD34PFBT) is a recently recognized neoplasm of mesenchymal origin." (PMID 38073992, 2023). "Immunohistochemistry showed that the tumor cells expressed CD34, CD31 (vascular +), and D2-40 (lymphatic +)." (PMID 38134102, 2023). "Immunohistochemical staining revealed that the tumor cells were positive for CD34, CD99, Bcl-2, and STAT6." (PMID 37491539, 2023). "In this study, CD34 expression was used to characterize the pathological status of tumor angiogenesis." (PMID 37353784, 2023). "We examined the tumor MVD using CD34 immunohistochemistry, and the results showed that the MVD in the CXCR7-silent group was reduced." (PMID 37057293, 2023). "The immunohistochemical examination is based on positivity for vimentin, desmin, CD34, hormone receptors (estrogens and progesterone, up to 80% of cases), S100, and a low Ki67 (<1% tumor cells)." (PMID 37629707, 2023). "Two main important stromal components, TLS and immature tumor stroma blood vessels (IBV_CD34+/SMA-), were influenced by αSMA_SS." (PMID 37568639, 2023). "Meanwhile, DFSP is a rare soft-tissue tumor that appears at the age of 20-50 years with a CD34 tumor marker present in the majority of such types of cancer." (PMID 37829962, 2023). "The CD34-related stem cell sialomucin, podocalyxin (PODXL), is a promising target as it is overexpressed on a variety of tumor types and its expression is consistently linked to poor prognosis." (PMID 38188285, 2023). "Anti-CD34 is a marker of vascular endothelial cells with high sensitivity and specificity of small and large vessels in both normal and tumor tissue." (PMID 37182187, 2023). "Postoperative pathology revealed multiple GISTs of high risk (NIH 2008 Revised GIST Hazard Grading System), and tumor cells were positive for CD117, DOG-1, and SMA; partially positive for CD34; and the Ki-67 index was 2%." (PMID 37311038, 2023). "They presented classical features (pleomorphic tumor cells, spindle cells, xanthomatous cells, eosinophilic granular bodies with reticulin staining surrounding individual cells, and CD34 immunopositivity), and a homozygous deletion of CDKN2A." (PMID 37349135, 2023).
tumor (continued). "Increased expression of CD34 confers tumour progression and aggressiveness on PCa accompanied by higher prostate‐specific antigen level, Gleason score, and the possibility of tumour recurrence." (PMID 37378426, 2023). "Here, in correlation with transcriptome data, we demonstrated the detectable protein expression of KDR, FLT4, UNC5A, ADAM12, CD34, and Prox-1 in the human KS tumor microenvironment." (PMID 37046832, 2023). "CD31 exhibits a distinct advantage over CD34, as it generates less background staining by predominantly highlighting endothelial-lined tumor emboli, thereby facilitating the more straightforward identification of tumor cells invading the vasculature." (PMID 37894944, 2023). "The presence of CD34-positive blood vessels within the tumor microenvironment indicates angiogenesis, which is a crucial process for tumor growth and spread." (PMID 38089632, 2023). "CD34, Prox-1, FLT4, and KDR are associated with endothelial cell signaling, vascularization, and angiogenesis during tumor formation." (PMID 37046832, 2023). "Tumor samples were immune stained for CD34, to estimate the microvessel density (MVD) in the RESP and REL specimens." (PMID 37345141, 2023). "Immunohistochemical investigation shows positivity for estrogen receptor (ER), progesterone receptor (PR), desmin, smooth muscle actin, and vimentin; some tumours are also CD34-positive." (PMID 36902513, 2023). "PDX LM maintained the clear cell phenotype despite passaging in mice, with a high incidence (>90%) of lung metastases formation at each passage, producing a higher density of tumor vessels stained with CD34." (PMID 37046045, 2023). "Examination under a microscope revealed tumor cells with extensive pleomorphism, high cytokeratin (CK) and CD34 positivity, and a low Ki67 index, all of which are consistent with SCPFT." (PMID 37692690, 2023). "Tumor stroma blood vessel maturation followed by the increase in MBV_CD34+/SMA+ density induced a low perineurial invasion." (PMID 37190085, 2023). "Immunohistochemical manifestations: The tumor cells displayed a mottled immune response to CD34 and diffused Vimentin expression." (PMID 37454137, 2023). "Immunohistochemical staining showed positive staining for CD34, corroborating the diagnosis of a CD34-positive fibroblastic tumor." (PMID 38021590, 2023). "The vascular morphology of the primary tumor areas on CD34 immunostaining indicated the presence of vessels with a large, irregular lumen, vessels without a lumen, and vessels with pillar formation within the vessel lumen in the well-differentiated cases." (PMID 36826036, 2023). "For instance, cluster designation 34 (CD34) staining has been used to evaluate the growth of neovascularization in HepG2 xenograft tumor-bearing mice, and CD31 staining can be used to identify the stages of HCC." (PMID 36925931, 2023). "Mature (MBV_CD34+/αSMA+) and immature (IBV_CD34+/αSMA-) stromal vessel density was assessed previously, and data were registered and used to study the influence of tumor stroma CAFs on their variability." (PMID 37568639, 2023). "CD34 is considered an established marker for vascular endothelial progenitors, potentially indicating tumor progression." (PMID 37627158, 2023). "Immunohistochemical staining revealed the tumor cells were positive for Vimentin, S-100, CD34 and MDM2." (PMID 37670330, 2023). "Liver tissues were stained for the key apoptotic executioner caspase 3, one of the main proliferation markers (Ki67) and CD34, the highly sensitive marker for endothelial cells and is generally used as a marker of angiogenesis in tumours." (PMID 36874031, 2023). "CD34 data suggests that metformin showed anti-proliferative effects on CD34 positive cells which are considered to be tumor initiating cells, however further experiments need to be warranted." (PMID 37903788, 2023). "We also observed that 66% of the cells in the KS tumors were CD34+, but only 34% of the tumor cells were also LANA+, and less than 6% were LANA+ only." (PMID 37046832, 2023).
tumor (continued). "Compared with non-responders, patients with a partial response showed a significantly lower risk of relapse when their residual tumor exhibited high FOXP3, CD68, CD83, CD31 and CD34 content and IL15 expression but a low CD138 concentration." (PMID 37511057, 2023). "CD34 had a trend of decreased expression with the increase of tumor malignancy, and the correlation was statistically significant; CD10 had no statistical significance in the differential and grading diagnosis of PT." (PMID 37933030, 2023). "NK3.3EVs reduced the CSC-like CD34+/CD38− subpopulation in imatinib-resistant and parental K562 cultures and decreased CSC-associated expression of tumor-promoting genes." (PMID 38201518, 2023). "We analyzed the main pathogenic pathways (MDM2 and CDK4), as well as the tumor microvascularization (CD31 and CD34) by immunohistochemical tests." (PMID 38132190, 2023). "The COX-derived prostanoids and gangliosides produced by melanoma tumor cells inhibit the differentiation of DCs from monocytes and CD34+ progenitors and trigger their apoptosis." (PMID 37190135, 2023). "To examine the effect of IEPA on the amount of IR- or ChT-induced ROS, we performed a DCFDA assay after the treatment of tumor cells and CD34+ HSPCs." (PMID 36903253, 2023). "The expression of CD34 (positioned on tumour vascular endothelium), VEGF and tumour endothelial marker (TEM8) decreased, suggesting the inhibition of tumour angiogenesis." (PMID 36463323, 2023). "Polymorphous low-grade neuroepithelial tumor of the young (PLNTY) is a low-grade tumor comprised of infiltrating “oligodendrocyte-like” cells that stain with CD34 immunopositivity." (PMID 36894761, 2023). "Expression of CD34 in tumor tissues was downregulated after morusin treatment, which correlated with less microvascular density (MVD) in the tumor tissues that had been treated with morusin." (PMID 37228582, 2023). "Immunohistochemistry indicated expression of actin and CD34, confirming the stromal origin of one component of the tumor." (PMID 36902642, 2023). "We propose here the quantification of CD34 and αSMA tumor stromal CAFs by using a stromal score (SS) which combines both intensity and density of stromal positive cells and H-score automatically generated by QuPath digital image analysis software." (PMID 37568639, 2023). "We quantified tumour volume and vasculature using microCT analysis and immunohistochemical staining for the endothelial marker CD34." (PMID 36922590, 2023). "Immunohistochemistry results showed positivity for TLE1, EMA, BCL-2, CKH, CK18, and Kiel-67 (in 46% of cells) in some regions of tumor cells; and negativity for Desmin, CD34, S-100, and CD117 in tumor cells." (PMID 38013382, 2023). "Both parameters had lower values compared to other molecular subtypes, HER2_BC being amongst the BC molecular subtypes with the lowest value of CD34 expression in tumor stroma cells." (PMID 37568639, 2023). "The study suggested that when it comes to blood vessel proliferation and the metastatic tendency of a tumor, CD34 can prove to be a useful tool and provide better diagnosis and patient care in cases of CRC." (PMID 38130549, 2023). "The tumours frequently contain eosinophilic granular bodies, a significant lymphocytic infiltrate, and CD34 immunopositive stellar cells." (PMID 36831464, 2023). "In vivo characterisation of VM vessels was initially assessed by histological examination of tumour tissues/xenografts stained with CD34/CD31 combined with PAS staining where VM channels appear as tubule-like structures containing red blood cells." (PMID 37052868, 2023). "Several earlier studies reported that CD41+CD42d+ MKs and CD34+ stem/progenitor cells are severally impaired due to their interactions with tumor cells, stromal cells or soluble cytokines, leading to the impairment of MK differentiation." (PMID 37055385, 2023).
tumor (continued). "We analyzed nine prognostic factors (age, Ki-67 Li, gender, primary tumor site, mutation genotype, expression of DOG-1, expression of CD117, expression of CD34, and group) using a univariate Cox regression analysis." (PMID 36983599, 2023). "Tumor growth and CD34 and Ki67 expression levels were assessed to determine the effects of D. indica on cell proliferation and angiogenic ability." (PMID 37057280, 2023). "Noteworthy, the immunostaining for CD34 was more intense in the vessels of tumor lesions from hyponatremic mice, with a statistically significant difference." (PMID 38069002, 2023). "The up-regulation of these 4 genes in tumor-bearing spleen (TS) Lin−/CD34+ HSPC compared to the same population in the homeostatic BM was confirmed by reverse transcription quantitative PCR (RT-qPCR)." (PMID 37134077, 2023). "The anti-tumour effects of green tea extracts were also evident in the ability of the administered extracts to reduce the percentage of CD34+ haematopoietic progenitor cells in acute promyelocytic leukaemia cells." (PMID 37511797, 2023). "Noteworthily, a retrospective study suggested that the mutations in KIT exon 11 were related to multiple factors, including age, gender, primary tumor location, tumor diameter, mitotic count and CD34 positivity." (PMID 37901323, 2023). "To differentiate this tumor from other tumors of different origins, we have done immunohistochemical staining by desmin, S-100 and CD34." (PMID 36609451, 2023). "The authors showed a correlation of Cho/NAA with MIB-1 and CD34 marker expression, as well as with tumor infiltration." (PMID 37345097, 2023). "We previously demonstrated that CD34+ HPC-derived DC subsets potently boost the expansion of tumor-reactive CD8+ T cells." (PMID 37728691, 2023). "Our earlier research using CD34 and α-smooth muscle actin (αSMA) immunohistochemistry showed a decrease of CD34-positive CAFs and an increase of αSMA-positive CAFs inside the tumor stroma." (PMID 37568639, 2023). "All NTRK-rearranged neoplasms are characterized by immunohistochemical positivity for CD34 and S100 and, molecularly, by fusions of NTRK1, NTRK2, and NTRK3 genes with variable partners; alternative RAF1 and BRAF fusions have also been described." (PMID 37876963, 2023). "Surgical specimens revealed spindle tumor cells surrounding the mammary ducts and were immunoreactive for both CD34 and STAT6, suggesting SFTs." (PMID 37315497, 2023). "Treatment with D. indica also significantly decreased the expression levels of CD34 and Ki67 (p < 0.05), further demonstrating its anti-angiogenic and anti-tumor potential in HCC." (PMID 37057280, 2023). "Cells derived from tumour to endothelial transdifferentiation express typical endothelial markers including CD34 and CD31, while tumour cells contributing to VM lack CD34 and CD31 expression." (PMID 36823554, 2023). "The present study showed a significant correlation between CD34 expression and the extent of the tumor (0.008, S)." (PMID 38130549, 2023). "SMA stained the smooth muscle cells in blood vessel lining and CD34 showed positive staining of endothelial cells of the blood vessels in the tumor." (PMID 36609451, 2023). "Outside of cluster 6, the neoplastic-appearing CD34+ cells were from tumor 1 (n = 66 CD34+), tumor 5 (n = 11 CD34+), and tumor 4 (n = 10 CD34+)." (PMID 36966348, 2023). "In this regard, according to a preview report, CD34+c-Kit+ early neutrophils with protumoral activity were indicated to be accumulated in a murine tumor model." (PMID 36921037, 2023). "It is also possible to produce DCs in vitro in large numbers (especially cDC2s and pDCs), from CD34+ precursors, capable of inducing a strong anti-tumor response in vitro, with activation of T-lymphocytes and NK cells by cDC2s and pDCs, respectively." (PMID 37190135, 2023). "Tumours were considered VM+ if they contained ≥1 VM (CD34−/PAS+) vessel in any of the 10 areas sampled for vessel counting." (PMID 37568738, 2023).